KRTAP5-8 (keratin associated protein 5-8)
Description:
In the hair cortex, hair keratin intermediate filaments are embedded in an interfilamentous matrix, consisting of hair keratin-associated protein (KRTAP), which are essential for the formation of a rigid and resistant hair shaft through their extensive disulfide bond cross-linking with abundant cysteine residues of hair keratins. The matrix proteins include the high-sulfur and high-glycine-tyrosine keratins.
Synonyms: KRTAP5.8; UHSKerB; KRTAP5-2
Tractability: No criterion of Open Targets' tractability assessment is met for any kind of drug.
Gene: Protein-coding gene on chromosome 11 (71,538,025 to 71,539,209, forward strand). Ensembl gene ENSG00000241233.
Pathways (Reactome):
Developmental Biology: Keratinization
Gene Ontology:
Molecular function: protein binding; structural constituent of skin epidermis
Cellular component: cytosol
Genetic constraint (gnomAD): Loss-of-function variants: 2 observed, 5.13 expected, observed/expected ratio (o/e) 0.39, 90% interval 0.16 to 1.22. That is too few expected variants to judge how well the gene tolerates losing a copy. Missense variants: 183 observed, 227.88 expected, observed/expected ratio (o/e) 0.8, 90% interval 0.71 to 0.91. Synonymous variants: 62 observed, 86.61 expected, observed/expected ratio (o/e) 0.72, 90% interval 0.58 to 0.88.
Homologues: Orthologues: mouse Krtap5-21 (80% identical), mouse Krtap5-23 (78% identical), mouse Krtap5-25 (77% identical). Paralogues in human: KRTAP5-5 (79% identical), KRTAP5-2 (71% identical), KRTAP5-6 (65% identical), KRTAP4-3 (42% identical), KRTAP4-11 (41% identical), KRTAP4-12 (41% identical), KRTAP4-6 (41% identical), KRTAP10-7 (40% identical), KRTAP10-6 (39% identical), KRTAP4-9 (39% identical), KRTAP4-5 (38% identical), KRTAP10-11 (37% identical), and 35 more.